APOC3 (apolipoprotein C3)
Diseases named in the same sentence as APOC3 in open-access papers (continued):
Sharing a sentence is not in itself a finding about the gene and the disease.
Thrombocytopenia (12 papers, 2017 to 2025). A reduction in the number of circulating thrombocytes. "Moreover, no adverse events related to thrombocytopenia were found, unlike what has been reported for volanesorsen, an antisense oligonucleotide-targeting APOC3 mRNA that showed results associated with thrombocytopenia in 76% of treated patients." (PMID 38203499, 2023). "In our experiments, the extent of apoC3 suppression was comparable to, or greater than, that achieved with Volanesorsen, raising the possibility that profound reductions in apoC3 may contribute mechanistically to platelet activation and, ultimately, thrombocytopenia." (PMID 41002378, 2025). "For example, while volanesorsen (ASO APOC3 inhibitor) is approved in the EU for the treatment of FCS39, it has not gained FDA approval because of concerns regarding bleeding and thrombocytopenia." (PMID 37355760, 2023). "Thrombocytopenia (platelet count < 150,000 × 109/L) has been reported in patients with FCS, treated or not with volanesorsen, a second generation APOC3 anti-sense oligonucleotide." (PMID 37370069, 2023).
chronic kidney disease (11 papers, 2011 to 2025). Impairment of the renal function secondary to chronic kidney damage persisting for three or more months. "Guanidinylated apolipoprotein C‐3 (ApoC3) increases the release of inflammatory cytokines and is associated with chronic kidney disease (CKD) and CKD‐associated vascular injury." (PMID 40563206, 2025).
endothelial dysfunction (11 papers, 2011 to 2025). In vascular diseases, endothelial dysfunction is a systemic pathological state of the endothelium (the inner lining of blood vessels) and can be broadly defined as an imbalance between vasodilating and vasoconstricting substances produced by (or acting on) the endothelium. "In this study, we examined the mechanisms by which APOC3 might cause endothelial dysfunctions and cellular inflammation." (PMID 27619170, 2016). "Guanidinylated apolipoprotein C-III (ApoC3) triggers pro-inflammatory signaling in monocytes and promotes endothelial dysfunction, directly linking modified lipoproteins to vascular inflammation." (PMID 40648948, 2025).
myocardial infarction (11 papers, 2012 to 2025). Gross necrosis of the myocardium, as a result of interruption of the blood supply to the area, as in coronary thrombosis. "A review of the EHR revealed only one of the two APOC3 19X carriers was free of myocardial infarction, revascularization, and other heart disease." (PMID 30255797, 2018). "Interestingly, one of the two APOC3 19X carriers identified here has evidence in the EHR of a myocardial infarction, revascularization, and other heart disease." (PMID 30255797, 2018).
breast carcinoma (8 papers, 1999 to 2022). "ApoC3 is glycosylated mainly with Galβ1-3 glycans, and we show here that is was overexpressed in breast cancer patients compared with healthy controls, suggesting a change in the glycosylation pattern of ApoC3." (PMID 28210565, 2017). "In contrast, the linkage among APOA1 rs670, APOC3 rs2854116 and APOC3 rs2854117 was lost in breast cancer patients, while significant linkage was only observed between the two APOA5 SNPs (D’=1.00)." (PMID 23829168, 2013). "The level of ApoC3 was slightly increased only in the early stage of breast cancer compared with that in the unbound-PI fraction (1.51 breast cancer:control ratio) and was present in elevated levels in the bound-PII fractions from patients with early and intermediate stages of breast cancer." (PMID 28210565, 2017). "However, there is no published information indicating an association of ApoC3 with breast cancer." (PMID 28210565, 2017). "The distributions of the tested SNPs (APOA1 rs670, APOC3 rs2854116, APOC3 rs2854117, APOA5 rs662799 and APOA5 rs2075291) fitted the Hardy-Weinberg equilibrium in both breast cancer patients and healthy controls." (PMID 23829168, 2013). "In this European multicentre study, we have examined the occurrence of APOC3 LOH and evaluated the effect of LOH of this chromosomal subregion on the clinical behaviour of the disease in a cohort of 766 breast cancer patients in more detail." (PMID 10360669, 1999). "We further examined the prognostic values of the mRNA expressions of APOA1, APOC3, APOA4, and APOA5 by using two online survival analysis software packages that were established through analyses of predominantly Western patients with breast cancer." (PMID 34226567, 2021).
COVID-19 (8 papers, 2021 to 2023). A disease caused by infection with severe acute respiratory syndrome coronavirus 2. "The deficiency in apolipoproteins levels in COVID-19 compared to normal human plasma (NHP) and ICU-ARDS patients was most pronounced for APOA1, APOA2, APOA4, APOC3 and APOE." (PMID 37031181, 2023). "Pathways depicting cholesterol, HDL and LDL metabolism (WP430, WP5109, WP4522, WP3601) are also among the top 10 pathways that have reduced activity in COVID-19 patients with significant reductions in APOA1, APOA2, APOC2, APOC3, APOB protein abundance." (PMID 36189295, 2022). "Genetic and epigenetic mosaicisms of non-polymorphic Alus as well as polymorphic Alus located in other genes, particularly the apolipoprotein cluster (APOA1, APOC3, APOA4) and HLA loci, could also influence the host response and disease outcomes of COVID-19." (PMID 33390179, 2021).
diabetic kidney disease (8 papers, 2014 to 2025). Progressive kidney disorder caused by vascular damage to the glomerular capillaries, in patients with diabetes mellitus. "APOC3, which plays a multifaceted role in triglyceride homeostasis, has been reported to exacerbate early-stage diabetic nephropathy by activating the renal TLR2/NF-κB pathway." (PMID 41438111, 2025). "In contrast, transgenic models of APOC3 overexpression not only display elevated plasma TG levels but also show exacerbated diabetic nephropathy, broadening our understanding of the systemic roles of APOC3 and its implications in metabolic diseases." (PMID 39684468, 2024). "Increased APOC3 levels in plasma have been reported in diabetic kidney disease patients and are increasingly considered an independent risk factor for the development of cardiovascular diseases in T2DM patients." (PMID 37686344, 2023). "What’s more ApoC3 overexpression aggravated early-stage diabetic nephropathy by activating the renal TLR2/NF-κB pathway with increased renal inflammation in mice." (PMID 37689737, 2023).
dyslipidaemia (8 papers, 2012 to 2024). "Of the genetic factors known to influence plasma triglyceride levels variation in APOC3- the gene for apolipoprotein (apo) C-III - has emerged as being particularly important as a regulator of triglyceride transport and a novel therapeutic target to reduce dyslipidaemia and CVD risk." (PMID 32849270, 2020). "APOC3, ANGPTL3, and ANGPTL4 are circulating proteins that are actively pursued as pharmacological targets to treat dyslipidaemia and reduce the risk of atherosclerotic cardiovascular disease." (PMID 38895109, 2024). "Apo-CIII levels and variation in the APOC3 gene contribute to dyslipidaemia, artery wall inflammation, atherogenesis, and cardiovascular disease (CVD) risk." (PMID 37834292, 2023).
hepatocellular carcinoma (8 papers, 2016 to 2025). A malignant tumor that arises from hepatocytes. "Analysis of publicly available long-read sequencing data from hepatoma cell lines (HepG2 and Huh7) and healthy liver tissue revealed the three novel APOC3 isoforms." (PMID 40282372, 2025). "We detected a novel isoform missing exon 2 in hepatoma cell lines (HepG2 and Huh7) when APOC3 transcripts were amplified using primers targeting exon 1a/b (forward) and 3 (reverse) and hence further investigated the presence of additional isoforms." (PMID 40282372, 2025). "Given that APOC3 is predominantly expressed in the liver, we analysed publicly available long-read transcriptomic datasets from immortalised human hepatoma cell lines, HepG2 and Huh7, as well as from healthy liver tissue to explore isoform diversity." (PMID 40282372, 2025). "Genes associated with lipid metabolism, such as APOA2, APOC3, APOC1, and APOE, were significantly upregulated in multiple cell types of hepatocellular carcinoma, indicating enhanced lipid metabolic activities." (PMID 39944086, 2025). "While our study mainly focused on hepatoma cell lines and healthy liver tissue, we also investigated the expression of APOC3 isoforms in small intestine models, specifically Caco-2 cells." (PMID 40282372, 2025). "In this study, we utilised publicly available long-read RNA-seq data from commonly used hepatoma cell lines (HepG2 and Huh7), liver tissue, and Caco-2 cells, a model of the small intestine, to investigate the isoform diversity of APOC3." (PMID 40282372, 2025). "The expression levels of ApoC3 mRNA and protein in the human hepatoma cell lines HepG2 and HepG2.2.15 were determined using real-time quantitative reverse transcription polymerase chain reaction (RT-qPCR) and Western blot." (PMID 29132372, 2017). "The upregulation of ApoC3 in cancer tissues has been reported in cancers including hepatocellular carcinoma and bladder cancer; besides, a significant decline of ApoC3 associated to colorectal cancer progression was also reported, which provides a significant statistical value for diagnosis." (PMID 36361568, 2022). "In order to further confirm the effects of miR-4271 on endogenous APOC3 expression, we sequenced nine of the human hepatoma cell lines (including HepG2, HuH-7, Hep3B, LM3, HLE, HLF, 97L, PLC, L02, etc.)and HepG2 was identified to be TT genotype, while 97L was identified to be GG genotype." (PMID 27624799, 2016). "All of these provide strong evidence that APOC3, APOH, HPX, and FGB can be used as biomarkers for hepatocellular carcinoma." (PMID 35449866, 2022).
Hyperglycemia (8 papers, 2011 to 2024). An increased concentration of glucose in the blood. "Furthermore, in the context of hyperglycemia, hepatic expression and activation of FoxO6 significantly contribute to increased ApoC3 production, impairing plasma TG metabolism associated with aging in HFD-fed conditions." (PMID 38441531, 2024).
acute pancreatitis (7 papers, 2019 to 2025). An acute inflammatory process that leads to necrosis of the pancreatic parenchyma. "In SHASTA-2, a study of patients with severe HTG, most subjects (>90%) treated with plozasiran, an apolipoprotein C-III (APOC3) small interfering RNA (siRNA), achieved TG levels <500 mg/dL (SI: 5.7 mmol/L), below the risk threshold for acute pancreatitis." (PMID 40642335, 2025). "Meanwhile, in the acute pancreatitis model, free fatty acids (FFAs) in the pancreas of Gpihbp1−/− mice were greater than in ApoC3-tg mice." (PMID 31570698, 2019).
Alzheimer disease (7 papers, 2009 to 2025). A progressive, neurodegenerative disease characterized by loss of function and death of nerve cells in several areas of the brain leading to loss of cognitive function such as memory and language. "A case–control study suggested that APOC3 SstI polymorphism was weakly associated with sporadic Alzheimer's disease in a Chinese population." (PMID 25380998, 2014). "However, with the exception of inconclusive reports evaluating relationships between APOC3 and Alzheimer's disease, the extent to which APOC3 is associated with cognitive impairment is largely unexplored." (PMID 19424489, 2009). "In T1DM, some of the terms annotated were related to myelin dysregulation (ARHGEF6, CNP, NADK2, PSAP, SLC25A12) and other neurological disorders, such as Alzheimer’s disease (i.e., POA2, APOC1, APOC3, CNP, GSK3B, PON1, PSAP, SELENBP1) or movement disorders." (PMID 39901093, 2025).
dementia (7 papers, 2019 to 2025). Loss of intellectual abilities interfering with an individual's social and occupational functions. "Higher apoE level in HDL that lacks apoC3 was associated with lower risk of dementia (hazard ratio per SD, 0.86; 95% CI, 0.76–0.99)." (PMID 40353050, 2025). "In contrast, the presence of apoE in high-density lipoproteins that contain apoC3 was unrelated to cognitive function and risk of dementia." (PMID 32648923, 2020). "In contrast, apoE in HDL that contained apoC3 was unassociated with cognitive function and risk of dementia or AD." (PMID 32648923, 2020). "Specifically, the presence of apoC3 in HDL appeared to modulate the association of apoE in HDL with risk of dementia and AD." (PMID 32648923, 2020). "In this case-cohort study including 1351 community-dwelling participants 74 years and older, the presence of apoE in high-density lipoproteins that lack apoC3 was associated with better cognitive function and decreased risk of dementia." (PMID 32648923, 2020). "In a prospective cohort of older adults with rigorous follow-up of dementia, the apoE level in HDL that lacked apoC3 was associated with better cognitive function and lower dementia risk." (PMID 32648923, 2020). "The findings of this study extend the beneficial associations of the novel apoE–positive, apoC3–negative lipoprotein from cardiovascular disease to dementia." (PMID 32648923, 2020). "Further studies are needed to clarify if the amount of apoE in HDL containing or lacking apoC3 or apoJ is associated with dementia via brain-specific or systemic pathways." (PMID 32648923, 2020). "In contrast with total apoE, a higher apoE level in HDL that lacked apoC3 was significantly associated with lower dementia risk." (PMID 32648923, 2020). "In this study, higher apoE levels in HDL lacking apoC3 in an older population were associated with better cognitive function and a lower risk of dementia or AD." (PMID 32648923, 2020). "However, in subset of the GEM sample with lipoprotein subspecies data, the association of ApoE level in HDL with incident dementia and cognitive function was found to depend on the presence or absence of ApoC3." (PMID 37666928, 2023). "The hazard ratios (HRs) for apoE level in HDL that contained or lacked apoC3 with dementia risk were statistically significantly different (HR per 1-SD higher apoE in HDL that contained apoC3: 1.07 [95% CI, 0.95-1.19] vs 0.86 [95% CI, 0.76-0.99]; P for heterogeneity = .03)." (PMID 32648923, 2020). "We hypothesized that higher apoE levels in HDL are inversely associated with risk of dementia but only in the absence of apoC3." (PMID 32648923, 2020). "Baseline low plasma ApoE level present in HDL lacking ApoC3 was a risk factor for incident dementia and worse cognitive function, but not in HDL having ApoC3." (PMID 37666928, 2023). "With regard to apoE subspecies, in the absence of apoC3, higher apoE in the HDL fraction of plasma was associated with better cognitive function and a lower risk of dementia and AD." (PMID 32648923, 2020). "The HR for dementia per 1-SD higher concentration of apoE in HDL that contained apoC3 was 1.11 (95% CI, 0.98-1.25) and was 0.87 (95% CI, 0.76-1.00) for apoE in HDL that lacked apoC3." (PMID 32648923, 2020).
gastric cancer (7 papers, 2011 to 2025). A primary or metastatic malignant neoplasm involving the stomach. "Research indicated that a reduced concentration of serum APOC3 might assist in the diagnosis of gastric cancer." (PMID 38972952, 2024). "Low expression of apolipoproteins including APOA1, APOA2, APOA4 and APOC3 in plasma exosomes of patients with hepatic-specific metastasis indicated an impaired function of lipid metabolism, which could participate in hepatic metastasis in gastric cancer cells." (PMID 37568802, 2023).
ischemic stroke (7 papers, 2016 to 2024). A stroke disorder caused by obstruction of blood flow to the brain, due to thrombotic (local blood clot formation) or embolic (due to a blood clot or other material traveling from another site) event. "In conclusion, the results of our study indicate that the APOC3 polymorphisms were significantly associated with the risk of ischemic stroke in the northern Chinese Han population." (PMID 27690381, 2016). "None of the genotype and allele frequencies of the rs2854116, rs2854117, rs4520 and rs5128 APOC3 variants significantly differed between the male ischemic stroke patients and healthy controls." (PMID 27690381, 2016). "In the present study, we examined the effects of four APOC3 polymorphisms (rs2854116, rs2854117, rs4520 and rs5128) on the risk of ischemic stroke in a northern Chinese Han population." (PMID 27690381, 2016). "The results of our study indicate that the APOC3 polymorphisms contribute to ischemic stroke susceptibility in females in the northern Chinese Han population." (PMID 27690381, 2016). "In the present study, we performed a hospital-based case—control study of 895 ischemic stroke patients and 833 control subjects to examine the effect of four SNPs (rs2854116, rs2854117, rs4520 and rs5128) of APOC3 on the risk of ischemic stroke in a northern Chinese Han population." (PMID 27690381, 2016). "Therefore, APOC3 plays an essential role in lipid metabolism, and this role could explain the potential association of rs4520 and rs5128 with ischemic stroke." (PMID 27690381, 2016). "Detecting APOC3 polymorphisms may increase awareness of the risk of ischemic stroke, and individuals in high-risk groups might be advised to receive regular checkups to reduce the adverse effects of ischemic stroke." (PMID 27690381, 2016). "AC3RL and ApoC3-free low-density lipoproteins (LDL) (AC3(-)L) were isolated from the plasma LDL of patients with ischemic stroke." (PMID 35453604, 2022). "Our findings indicate some degree of gender specificity in the effect of APOC3 genetic variation on ischemic stroke." (PMID 27690381, 2016). "Therefore, SNPs in the APOC3 gene may affect ischemic stroke susceptibility." (PMID 27690381, 2016). "Therefore, the gender difference in the effect of APOC3 genetic variation on ischemic stroke is likely attributable to epigenetic modifications such as DNA methylation." (PMID 27690381, 2016). "In contrast, neither the genotype nor the allele frequencies of the APOC3 SNPs significantly differed between the male ischemic stroke patients and controls." (PMID 27690381, 2016). "However, a combination of APOC3 and APOA1 markers improved the differentiation between hemorrhagic and ischemic stroke." (PMID 31242583, 2019).
liver cancer (7 papers, 2014 to 2025). An epithelial or non-epithelial malignant neoplasm that arises from the liver. "The identified connections with key lipid/triglyceride metabolism biomarkers, namely PPARA, APOC3, and APOA5, suggest the involvement of SELENOP in lipid homeostasis within the context of liver cancer." (PMID 39001444, 2024). "The results showed that the expression of PAIP1 had a significant negative correlation (P < 0.05) with that of APOC3, CCL14, IL1RN, SERPINA3, and HAMP in liver cancer tissues." (PMID 37101794, 2023).
coronary atherosclerosis (6 papers, 2012 to 2023). Atherosclerosis of the coronary vasculature. "It has long been known that plasma APOC3 concentrations correlate with TG levels, are elevated in patients with diabetes, and associate with increased coronary atherosclerosis and CVD risk." (PMID 34981790, 2022). "Shuldiner and colleagues showed that loss-of-function APOC3 variants in the Amish associated with reduced TG levels and decreased coronary atherosclerosis." (PMID 34981790, 2022).